ASAP1 (ArfGAP with SH3 domain, ankyrin repeat and PH domain 1)
Description:
Possesses phosphatidylinositol 4,5-bisphosphate-dependent GTPase-activating protein activity for ARF1 (ADP ribosylation factor 1) and ARF5 and a lesser activity towards ARF6. May coordinate membrane trafficking with cell growth or actin cytoskeleton remodeling by binding to both SRC and PIP2. May function as a signal transduction protein involved in the differentiation of fibroblasts into adipocytes and possibly other cell types. Part of the ciliary targeting complex containing Rab11, ASAP1, Rabin8/RAB3IP, RAB11FIP3 and ARF4, which direct preciliary vesicle trafficking to mother centriole and ciliogenesis initiation.
Synonyms: DDEF1; KIAA1249; PAG2; PAP; ZG14P; CENTB4; AMAP1
Tractability: Antibody: its Gene Ontology location is reachable by antibodies, with high confidence. PROTAC: ubiquitination databases record sites on it; its protein half-life has been measured.
Gene: Protein-coding gene on chromosome 8 (130,052,104 to 130,443,762, reverse strand). Ensembl gene ENSG00000153317.
Subcellular location: Cytoplasm; Membrane; Golgi apparatus; Golgi apparatus, trans- Golgi network
Subcellular location (Human Protein Atlas): Golgi apparatus; Plasma membrane; Centriolar satellite
Pathways (Reactome):
Organelle biogenesis and maintenance: VxPx cargo-targeting to cilium
Gene Ontology:
Molecular function: cadherin binding; protein binding; GTPase activator activity
Biological process: cilium assembly; protein localization to cilium; positive regulation of membrane tubulation
Cellular component: Golgi apparatus; Golgi membrane; trans-Golgi network membrane; cytosol; plasma membrane; podosome; cytoplasm; membrane
Genetic constraint (gnomAD): Loss-of-function variants: 37 observed, 110.97 expected, observed/expected ratio (o/e) 0.33, 90% interval 0.25 to 0.44. The upper end of that interval is the gene's LOEUF score, 0.44, which puts it in group 1 of 6, group 1 being the genes least tolerant of losing a copy. Missense variants: 915 observed, 1,246.8 expected, observed/expected ratio (o/e) 0.73, 90% interval 0.69 to 0.77. Synonymous variants: 504 observed, 486.99 expected, observed/expected ratio (o/e) 1.03, 90% interval 0.96 to 1.11.
Homologues: Orthologues: chimpanzee ASAP1 (99% identical), macaque ASAP1 (99% identical), rat Asap1 (97% identical), guinea pig ASAP1 (97% identical), rabbit ASAP1 (96% identical), pig ASAP1 (95% identical), mouse Asap1 (95% identical), tropical clawed frog asap1 (84% identical), zebrafish asap1b (78% identical), zebrafish asap1a (76% identical). Paralogues in human: ASAP2 (53% identical), ASAP3 (36% identical), ACAP3 (17% identical), ACAP2 (17% identical), ARAP2 (17% identical), ARAP3 (16% identical), ARAP1 (16% identical), ACAP1 (15% identical), AGAP2 (14% identical), AGAP1 (13% identical), AGAP3 (13% identical), AGAP6 (11% identical), and 16 more.
Diseases named in the same sentence as ASAP1 in open-access papers:
ASAP1 is named in the same sentence as 58 diseases in open-access papers, as found by Europe PMC text mining. Sharing a sentence is not in itself a finding about the gene and the disease. The quoted sentences say what the papers report.
breast carcinoma (14 papers, 2009 to 2025). "Further research is warranted to elucidate the underlying mechanisms and validate the clinical utility of ASAP1 in breast cancer prognosis." (PMID 37762658, 2023). "Studies have shown that ASAP1 is associated with tumor development and malignant metastasis in prostate cancer, hepatocellular carcinoma, breast cancer, head and neck squamous cell carcinomas, prostate cancer, colorectal cancer, and ovarian cancer." (PMID 36792578, 2023). "In a luminal breast cancer mouse model, loss of ASAP1 expression increased AKT signal activation and tumor cell invasion." (PMID 37762658, 2023). "Breast cancer invasiveness has been linked to ASAP1 activation by ARF6, which is in turn activated by EGFR ligation to GEP10035." (PMID 27910913, 2016). "Two genes, Asap1 and Prox1, respectively implicated in breast cancer metastasis and progenitor cell function in other systems, were selected for further analysis as their roles in the normal mammary gland were unknown." (PMID 25879659, 2015). "In breast cancer, ASAP1 interacts with the SH3 domain of cortactin via its proline‐rich sequence and binds to paxillin via its own SH3 domain, playing a role in promoting invasion." (PMID 40742091, 2025). "These contradictory results highlight the need for further research to fully understand the role of ASAP1 in breast cancer." (PMID 37762658, 2023). "This highlights the significance of ASAP1 as a prognostic indicator that can help predict outcomes in this specific subset of breast cancer patients." (PMID 37762658, 2023). "Of 452 breast cancer cases, 176 cases showed high ASAP1 expression, and 276 cases showed low ASAP1 expression." (PMID 37762658, 2023). "Overexpression of ASAP1 was identified in cancer cell lines including uveal melanoma, prostate cancer, breast cancer, and colorectal cancer, indicating that ASAP1 promotes cancer invasion and metastasis." (PMID 36110251, 2022). "ASAP1 has been shown to be overexpressed and enhanced in several malignancies and is functionally correlated with breast cancer metastasis." (PMID 27694689, 2016). "Asap1 is a multi-domain member of the ARF-GAP protein family and has roles in metastasis in several systems including breast cancer cell lines, in which it has been implicated in invasion and metastatic potential." (PMID 25879659, 2015). "We have shown previously that an Arf6 pathway, in which Arf6 is activated by GEP100 and employs AMAP1 (also called DDEF1 or ASAP1) as its downstream effector, is pivotal for the invasion and metastasis of different breast cancer cells." (PMID 24621372, 2014). "Like breast cancer cells, siRNA-mediated knockdown of ASAP1 protein expression in prostate cancer cells has been shown to effectively block their migration and invasion." (PMID 19416474, 2009). "ASAP1 expression may serve as a potential prognostic biomarker for personalized treatment decisions in breast cancer patients." (PMID 37762658, 2023). "ASAP1 has been shown to be necessary for the in vitro invasive potential and in vivo metastatic potential of specific breast cancer cell lines including MDA-MB-231 cells, while increased Prox1 expression promotes the transition of intestinal adenomas to high-grade dysplasia or carcinoma in situ." (PMID 25879659, 2015). "Furthermore, ASAP1 expression in uveal melanoma, mammary carcinoma, and prostate cancer correlates with tumour invasiveness." (PMID 25682866, 2015). "It has been reported that this ASAP1-Y782F mutant inhibits podosome/invadopodia formation in MDA-MB-231 breast cancer cells, although its effect on ECM degradation is unknown." (PMID 25682866, 2015). "Moreover, expanding research to larger patient cohorts and diverse breast cancer subtypes could provide more comprehensive insight into the clinical relevance and generalizability of ASAP1 as a prognostic and therapeutic target." (PMID 37762658, 2023).
breast carcinoma (continued). "After BRAG2 binding to phosphorylated EGFR, ARF6 is activated in breast cancer cells, leading to the formation of invadopodia with recruitment of Cortactin, Paxillin and the ARF GAP ASAP1." (PMID 32426352, 2020). "Notably, ASAP1 plays a critical role in the EMT process across different cancers and has been shown to promote EMT in ovarian, gastric, and breast cancers." (PMID 40742091, 2025). "ADP-ribosylation factor-GTPase activating protein (Arf-GAP), with an SH3 domain, ankyrin repeat, and PH domain-containing protein 1 (ASAP1, also called DDEF1 or AMAP1), is highly expressed on breast cancer cells and mediates breast cancer invasion and metastasis." (PMID 36555115, 2022). "We have shown that an Arf6 pathway, in which Arf6 is activated by GEP100, a guanine nucleotide exchanging factor (GEF) for Arf-GTPases, and employs AMAP1 (also called DDEF1 or ASAP1) as its downstream effector, is pivotal for the invasion and metastasis of different breast cancer cells." (PMID 24621372, 2014).
prostate carcinoma (7 papers, 2009 to 2023). A carcinoma that arises from epithelial cells of the prostate gland. "The ASAP1 protein is also overexpressed in 80% of primary prostate cancers, in which its expression is substantially higher in metastatic lesions; and moreover, additional copies of its gene are detected in 58% of primary prostate cancer specimens." (PMID 19416474, 2009). "Copy number variations in regions encompassing important prostate cancer genes, such as PTEN and CHD1 or ASAP1, MYC, and HDAC9, are predictive of cancer significance and represent useful biomarkers to distinguish low-risk prostate cancer from intermediate- and high-risk prostate cancer." (PMID 31366128, 2019). "In addition, in prostate cancer, CKAP2, LASP1, BIRC5, WASF1, ASAP1 and RUNX2 mRNAs were recently identified as new miR-203 targets, suggesting that miR-203 could be a new prognostic marker and a therapeutic target in metastasis of prostate cancer." (PMID 23285092, 2012).
tuberculosis (6 papers, 2015 to 2024). A chronic, recurrent infection caused by the bacterium Mycobacterium tuberculosis. "Susceptibility to human tuberculosis was associated with variants in the ASAP1 gene encoding a regulator of dendritic cell migration." (PMID 38892353, 2024). "Susceptibility to human tuberculosis is associated with variants in the ASAP1 gene, which encodes a regulator of dendritic cell (DC) migration." (PMID 38892353, 2024). "ASAP1 plays a role in regulating the migration of dendritic cells, with a possible impact on predisposition to tuberculosis." (PMID 33731010, 2021). "The genetic variant rs4733781 of the ASAP1 gene was revealed as a significant locus for tuberculosis (TB) susceptibility, but the results still need to be validated." (PMID 31089398, 2019). "The SNP rs10956514 lying in the coding sequence of ASAP1 is associated with susceptibility to tuberculosis and also moderately associated with T2D (but not with Type 1 Diabetes) risk." (PMID 37686290, 2023). "Recently, ASAP1 polymorphisms have been reported to be associated with human susceptibility to tuberculosis (TB) according to a large-scale genome-wide association study (GWAS); ASAP1 expression affects dendritic cell migration, which may be involved in TB predisposition." (PMID 33194781, 2020). "However, after DCs migrated to the lymph nodes, and T-cells being activated after adaptive immunity, we postulated that the expression of ASAP1 would be stimulated by T-cell-based immunity during tuberculosis disease progression." (PMID 31089398, 2019). "Two genome-wide significant results were recorded for tuberculosis, belonging to WT1 gene and ASAP1 gene." (PMID 26524966, 2015). "In our study, we found ASAP1 expression was high among the LTBI group and much higher in TB patients, which indicated that ASAP1 expression was increased after Mycobacterium tuberculosis infection, especially in TB disease status." (PMID 31089398, 2019).
colorectal cancer (5 papers, 2017 to 2023). A primary or metastatic malignant neoplasm that affects the colon or rectum. "Overexpression of ASAP1 has been reported to be associated with poor metastasis-free survival in prostate, colorectal cancer, and ovarian cancer and malignant phenotypes of primary BCs." (PMID 32235890, 2020). "ASAP1 and RIPK2 were reported as hub proteins of inflammatory bowel disease and colorectal cancer; and ASAP1 expression might be associated with pulmonary and bladder neoplasms." (PMID 35477477, 2022). "Hsa_circ_104689 is spliced from ASAP1 (ArfGAP with SH3 domain, ankyrin repeat and PH domain 1), which encodes an oncoprotein associated with colorectal cancer, laryngeal squamous cell cancer and epithelial ovarian cancer." (PMID 28484086, 2017).
ovarian carcinoma (5 papers, 2020 to 2024). A malignant neoplasm originating from the surface ovarian epithelium. "We showed previously that ASAP1 was highly expressed in ovarian carcinoma and was associated with poor patient survival." (PMID 34405025, 2021). "Previous studies have shown that FAK promotes ovarian cancer proliferation, invasion, and metastasis by interacting with apoptotic peptidase-activating factor 1 (ASAP1)." (PMID 38560575, 2024). "Based on the correlation of ASAP1 with FAK in ovarian carcinoma and oncogenic properties, it is an attractive approach to target both ASAP1 and FAK for OC therapy." (PMID 34405025, 2021). "Therefore, our research suggests that ASAP1 mutation might be related to RIPK2 alteration and thus be associated with Taxol resistance in ovarian cancer." (PMID 35477477, 2022).
uveal melanoma (5 papers, 2009 to 2023). A melanoma derived from melanocytes of the uveal tract. "Amplified AGAP2 and ASAP1 were associated with impaired OS and progression-free survival in uveal melanoma." (PMID 37182141, 2023).
hepatocellular carcinoma (4 papers, 2020 to 2023). A malignant tumor that arises from hepatocytes. "Increased expression of ASAP1 was correlated with poor prognosis in head and neck squamous cell carcinoma, hepatocellular carcinoma, gastric cancer, epithelial ovarian cancer, clear cell renal cell carcinoma, and pancreatic cancer." (PMID 37762658, 2023). "The clinicopathological implications of ASAP1 expression in patients with hepatocellular carcinoma (HCC) remain unclear." (PMID 36110251, 2022). "In addition, circASAP1, a circRNA derived from exons 2 and 3 of the ASAP1 gene, was overexpressed in hepatocellular carcinoma (HCC) cell lines with high metastatic potential and in metastatic HCCs." (PMID 33319172, 2020).
gastric cancer (3 papers, 2022 to 2023). A primary or metastatic malignant neoplasm involving the stomach. "FAK was associated with ASAP1 in gastric cancer and associated with poor patient survival, indicating that FAK may play a synergistic role in gastric tumorigenesis and metastasis." (PMID 35574330, 2022).
head and neck squamous cell carcinoma (3 papers, 2022 to 2023). A squamous cell carcinoma that arises from any of the following anatomic sites: lip and oral cavity, nasal cavity, paranasal sinuses, pharynx, larynx, and salivary glands. "Increased ASAP1 expression in different types of cancer, including colon cancer, head and neck squamous cell carcinoma, epithelial ovarian cancer, renal cancer, pancreas cancer, gastric cancer, and triple-negative breast cancer, was associated with poor prognosis and aggressive clinical features." (PMID 36110251, 2022).
melanoma (3 papers, 2020 to 2022). A malignant, usually aggressive tumor composed of atypical, neoplastic melanocytes. "Consistently, DGAT1, ASAP1, MYC, and GDF6 are co-amplified in melanoma and other cancers." (PMID 35732120, 2022). "An extra copy of chromosome 8q, containing the DGAT1 locus but also other putative melanoma oncogenes ASAP1/DDEF, MYC, and GDF6, has been observed in approximately 30% of melanoma cases." (PMID 35732120, 2022).
pancreatic cancer (3 papers, 2022 to 2023). "ASAP1 was also associated with PD-L1 expression in pancreatic cancer fibrosis." (PMID 35574330, 2022).
glioblastoma (2 papers, 2021 to 2022). The most malignant astrocytic tumor (WHO grade IV). "Since EIF4A3 is involved in various RNA metabolic processes, including nonsense-mediated RNA decay and RNA splicing, for example, EIF4A3-induced circular RNA ASAP1 (circASAP1) facilitates tumorigenesis and temozolomide resistance of glioblastoma via NRAS/MEK1/ERK1/2 signaling pathway." (PMID 34408982, 2021).
hepatoblastoma (2 papers, 2016 to 2023). Hepatoblastoma (HB) is a malignant hepatic tumor and is the most common pediatric liver cancer. "In hepatoblastoma, the loss of ASAP1 and EGFR expression was observed in histologically poor differentiated cases, and this trend was more pronounced in metastatic and unresectable cases." (PMID 37762658, 2023).
metastatic prostate carcinoma (2 papers, 2012 to 2023). A carcinoma that arises from the prostate gland and has spread to other anatomic sites. "Interestingly, another group of targets is associated with germ cells, including Asap1 (Ddef1), which encodes an ADP-ribosylation factor GTPase-activating protein implicated in metastatic prostate cancer, and also the Wilms' tumour gene WT1." (PMID 22479388, 2012).
ovarian tumor (2 papers, 2021 to 2022). "Taken together, FAK PROTAC inhibits both FAK kinase activity and its scaffold protein activity by disrupting the interaction between FAK and ASAP1 and is highly effective in inhibiting ovarian tumor growth and metastasis." (PMID 35574330, 2022). "We synthesized HL142 and test its antitumor activities in OC and found that HL142 suppressed ovarian tumor growth and metastasis by inhibiting ASAP1, FAK and reversing EMT through attenuating the FAK and TGFβ pathways." (PMID 34405025, 2021). "We recently reported that FAK is co-expressed and interacts with ASAP1 in OC, which may regulate ovarian tumor metastasis and chemoresistance." (PMID 35574330, 2022). "ASAP1, FAK, and EMT markers were also confirmed by Western blotting in primary ovarian tumors and their expression levels in vivo were consistent with the data obtained in vitro." (PMID 34405025, 2021).
pulmonary TB (2 papers, 2022). "A study of 7.6 million genetic variants in 5530 patients with pulmonary TB and 5607 healthy controls recruited in Russia confirmed an association between TB susceptibility and variants of ASAP1 gene that encodes the DC migration regulator." (PMID 35967869, 2022). "An analysis of 5530 patients with pulmonary TB and 5607 healthy controls showed that the DC migration regulator, ArfGAP with SH3 domain, ankyrin repeat, and PH domain 1 (ASAP1), was associated with susceptibility to TB." (PMID 35967869, 2022). "To understand if the population diversity and genetic heredity could influence the association of SNPs in ASAP1 and SP110 with the susceptibility of TB, we selected a set of SNPs and focused on genetic polymorphisms relating to pulmonary TB in a minority Mongolian population in China." (PMID 36249417, 2022).
bovine tuberculosis (1 paper, 2024). "Impaired migration of mycobacteria-infected DCs, caused by the genetically determined excessive reduction of ASAP1 expression, may contribute to human and bovine tuberculosis." (PMID 38892353, 2024).
breast tumors (1 paper, 2020). "While CNA events in deep or shallow depletion rarely or less occurred, EGFR, MYC, IRF2BP2, ASAP1, and CCT5 (except for DRD1) often underwent copy gain and amplification, acquiring CNA-driven expression in the breast tumors." (PMID 32235890, 2020). "We next sought to address the correlation between CNA frequencies and expression levels of MYC, EGFR, ASAP1, IRF2BP2, CCT5, and DRD1 in broad BC cell lines and breast tumors and the clinical relevance of the genes to patients with BC." (PMID 32235890, 2020).
colon cancer (1 paper, 2021). "Given that oxaliplatin is also a standard chemotherapeutic agent used in colon cancer treatment, we also examined the expression of molecular signature genes PIK3CA, SLC6A6, ASAP-1 and TMEM-43 in colon cancer cells resistant to this drug." (PMID 34571860, 2021). "To test whether PIK3CA, SLC6A6, TMEM-43, and ASAP-1 expression is driven by CLDN1 and CLDN7 expression, we analyzed these genes and proteins in CLDN1-overexpressing SW480 (SW480CLDN1) and CLDN7-knockdown DLD-1 (DLDCLDN7KD) colon cancer cell lines." (PMID 34571860, 2021).
developmental delay (1 paper, 2025). "For instance, CA10 is implicated in bone metabolism and bone development, ASAP1 is an important candidate gene affecting the growth and body size of Tibetan sheep, and biallelic variants of CSMD1 cause developmental delay." (PMID 40128652, 2025).
glioma (1 paper, 2021). A benign or malignant brain and spinal cord tumor that arises from glial cells (astrocytes, oligodendrocytes, ependymal cells). "Among the novel genetic loci they uncovered was a SNP near ASAP1, a locus previously associated with glioma." (PMID 34440309, 2021).